CD40 (CD40 molecule)
Diseases named in the same sentence as CD40 in open-access papers (continued):
Sharing a sentence is not in itself a finding about the gene and the disease.
Hepatic fibrosis (4 papers, 2013 to 2021). The presence of excessive fibrous connective tissue in the liver. "CD40 agonists are also known to induce liver inflammation, although their role in remodeling the pro-metastatic niche and liver fibrosis remains ill-defined." (PMID 34202272, 2021). "By contrast, overexpression of IDO1 significantly aggravated liver fibrosis, accompanied by a dramatically reduced percentage of CD11c+MHCII+, CD11c+CD40+ cells and CD3+, CD3+CD4+ T cells in hepatic NPCs of fibrotic livers." (PMID 33414436, 2021). "Moreover, overexpression of liver‐specific IDO1 diminished numbers of splenic CD11c+MHCII+, CD11c+CD40+ cells and reduced CD3+, CD3+CD4+ T cells infiltration subsequently during BDL-induced hepatic fibrosis." (PMID 33414436, 2021). "This hypothesis was further validated in our research reported here, in IDO1-KO mice model, where exhibited markedly attenuated liver fibrosis, together with an elevated percentage of CD11c+MHCII+, CD11c+CD40+ cells in hepatic NPCs of fibrotic livers." (PMID 33414436, 2021).
Hepatic steatosis (4 papers, 2015 to 2021). Steatosis is a term used to denote lipid accumulation within hepatocytes. "CD154, as a ligand of CD40 and key mediator of inflammation, may play a protective role in hepatic steatosis through a possible connection to PERK-eIF2α-CHOP arm." (PMID 34236076, 2021).
Hypercholesterolemia (4 papers, 2016 to 2025). An increased concentration of cholesterol in the blood. "Opposite to our findings, CD40 deficiency on follicular B cells was described as protective in LDL receptor-deficient mice, which suffer from severe hypercholesterolemia." (PMID 39899926, 2025). "For instance, it has been shown that the CD40/CD40L levels in rats with hypercholesterolemia are downregulated by trans-resveratrol administration." (PMID 26799794, 2016). "CD40/CD40L contributes to hypercholesterolemia-induced microvascular inflammation." (PMID 34161419, 2021). "In particular, it was shown previously that there is a relationship between the CD40/CD40L system and cholesterol metabolism in patients with moderate hypercholesterolemia." (PMID 36979953, 2023).
hyperthyroidism (4 papers, 2020 to 2024). Overactivity of the thyroid gland resulting in overproduction of thyroid hormone and increased metabolic rate. "So, we speculate that overexpression of CD40 is an underlying mechanism that predispose PCOS patients to hyperthyroidism." (PMID 38586452, 2024). "Multiple studies have shown that CD40 was significantly highly expressed in patients with hyperthyroidism and contributed to GD pathogenesis in several pathways." (PMID 38586452, 2024). "On the other hand, overexpression of CD40 is able to activate downstream cytokines, such as IL6, which increase the production of thyroid-specific autoantibodies and promote hyperthyroidism." (PMID 38586452, 2024).
ischemia (4 papers, 2018 to 2022). A hypoperfusion of the BLOOD through an organ or tissue caused by a PATHOLOGIC CONSTRICTION or obstruction of its BLOOD VESSELS, or an absence of BLOOD CIRCULATION. "Except for thrombosis, platelets can directly interact with circulatory leukocytes by changing the surface expression of P-selection or CD40 to form platelet-leukocyte aggregates activating the innate immune response to ischemia." (PMID 35959219, 2022). "Platelets interact directly with circulating leukocytes by changing the surface expression of P-selectin or CD40, thereby forming platelet-leukocyte aggregates and activating the innate immune response to ischemia." (PMID 35370926, 2022). "In response to agonistic anti-CD40 antibody treatment, sickle cell mice developed an acute hepatitis with histological features of vessel-occlusion and ischemia." (PMID 33763072, 2021).
Listeria monocytogenes infection (4 papers, 2012 to 2022). "The decreased expression of CD86, I-Ab, CD80, and CD40 was also observed in Mettl3KO splenic DC after Listeria monocytogens infection." (PMID 31015515, 2019). "Recent studies have shown, that the synergy of TLR2 and CD40 signaling contributes to activation of resting B cells and TLR2 signaling controls an early Listeria monocytogenes infection which involve co-stimulatory molecule CD40." (PMID 24341851, 2013). "For example, CD40-deficient CD8 T cells were only tested in Listeria infection in a setting that was independent of CD40-mediated help." (PMID 35543702, 2022). "Our results show that CD40-activated B cells can directly present antigen to naïve CD8+ T cells to induce the generation of potent effectors able to secrete cytokines, kill target cells and control a Listeria monocytogenes infection." (PMID 22291907, 2012).
lung adenocarcinoma (4 papers, 2010 to 2025). A carcinoma that arises from the lung and is characterized by the presence of malignant glandular epithelial cells. "Lung adenocarcinoma A549 cells were chosen as target cells and CD40 signal was stimulated by sCD40L." (PMID 20673484, 2010). "Gene expression profiles of CD40, BAFFR, RANK and LTβR had similar patterns in the LUSC (lung squamous cell carcinoma) and LUAD (lung adenocarcinoma) subgroups analyzed and both were similar to control samples." (PMID 31137630, 2019). "CD40 and CEACAM5 were the top DCGs in the lung adenocarcinoma group, and both play important roles in cancer biology." (PMID 26029238, 2015).
metastatic melanoma (4 papers, 2019 to 2024). A melanoma that has spread from its primary site to another anatomic site. "CD40, a member of the TNF receptor superfamily, enhances T-cell activity and has shown promise in clinical trials with CD40 agonistic antibodies combined with immune checkpoint inhibitors for treating metastatic melanoma." (PMID 39355255, 2024). "The observations here point to the potential usefulness in examining CD40 expression as a possible prognostic marker for response to ICB therapy as well as a need for new clinical trials combining RGS with ICB in metastatic melanoma patients." (PMID 34092233, 2021). "Only one phase I/II clinical study has been investigated administrating anti-CTLA4 antibody with anti-CD40 agonist (CD40; M1-TAMs marker) in metastatic melanoma." (PMID 32756500, 2020).
nasopharyngeal carcinoma (4 papers, 2010 to 2020). A carcinoma arising from the nasopharyngeal epithelium. "The expression of CD40 on cholangiocarcinoma and the increased levels of expression detected after IFN-γ stimulation are consistent with previous studies reporting CD40 expression on other carcinomas e.g. nasopharyngeal carcinoma." (PMID 21103345, 2010).
ocular toxoplasmosis (4 papers, 2010 to 2023). Ocular toxoplasmosis is an infection in the eye caused by the parasite, Toxoplasm a gondii. "Moreover, T. gondii-infected CD40 deficient mice had lower Beclin 1 levels in their brain microglia/macrophages and Beclin 1-deficient mice were susceptible to cerebral and ocular toxoplasmosis." (PMID 21217818, 2010). "Here, we present a rare case of bilateral ocular toxoplasmosis and concurrent subacute toxoplasma encephalitis in a 70-year-old patient on anti-CD40 treatment following his liver transplant." (PMID 37545749, 2023). "CD40 is a stimulator of autophagy that confers resistance against cerebral and ocular toxoplasmosis." (PMID 31119109, 2019). "CD40–/– transgenic mice where CD40 expression is rescued in endothelial cells were used to examine further the role of endothelial CD40 during the development of cerebral and ocular toxoplasmosis." (PMID 34179003, 2021). "However, it is important to note that cerebral and ocular toxoplasmosis in CD40–/– and CD154–/– mice precede the development of CD8+ T cell exhaustion." (PMID 34179003, 2021). "Rather than reducing transmigration of infecting leukocytes across endothelial cells, CD40 likely conferred protection against cerebral and ocular toxoplasmosis because the presence of CD40 reduced the number of parasite foci in neural endothelial cells, diminishing invasion of the CNS." (PMID 34179003, 2021). "Importantly, studies in CD154−/− and CD40−/− mice established that this pathway is central for restricting parasite load in the brain and retina, and protecting against cerebral and ocular toxoplasmosis, the two main forms of disease in humans." (PMID 31119109, 2019). "Studies in humans and mice revealed that CD40 and its main ligand CD154 are central for protection against cerebral and ocular toxoplasmosis." (PMID 34179003, 2021).
ovarian tumors (4 papers, 2011 to 2025). "MoDCs readily engulfed HOCl-oxidized SKOV3 ovarian tumor cells, and when matured with either monophosphoryl lipid A or anti-CD40 activating antibody, they could stimulate strong T cell responses directed against specific ovarian tumor-associated antigens such as HER-2/neu and MUC1." (PMID 22082029, 2011).
peritonitis (4 papers, 2011 to 2023). Inflammation of the peritoneum (tissue that lines the abdominal wall and covers most of the organs in the abdomen). "This suggests that CD40 maybe a target gene for A20 in vitro to restrict the inflammatory response in PD-associated peritonitis." (PMID 24747594, 2014). "Moreover, neutrophil recruitment in a model of thioglycollate-induced peritonitis is impaired in CD40-deficient mice." (PMID 21876738, 2011). "In addition, we observed that neutrophil recruitment in a model of thioglycollate-induced peritonitis is impaired in CD40-deficient mice." (PMID 21876738, 2011). "TMs decreased the association of HuR with genes involved in chemotaxis and immune response, including Cxcl10, Il1b and Cd40, reducing their expression and protein secretion in primary murine bone marrow-derived macrophages and in an LPS-induced peritonitis model." (PMID 36912171, 2023).
Pleural effusion (4 papers, 2021 to 2024). The presence of an excessive amount of fluid in the pleural cavity. "This study shows that CD16+ monocytes isolated from pleural effusion of TPE patients exhibit a more mature phenotype than CD16- monocytes, such as costimulatory molecules CD40, CD80, CD86 and HLA-DR." (PMID 34237073, 2021). "Conforming with previous studies which mostly used peripheral blood samples, our pleural effusions study also confirmed the elevated levels of CA12, CD40, IL-6, IL-8, PD-L1, and VEGFA, proposing their potential either as biomarkers for severity and prognosis of the disease or targets for therapy." (PMID 36428847, 2022).
relapsing-remitting MS (4 papers, 2015 to 2025). "Lastly, attempts have been made to counteract dysregulated CD40 signaling in MS: defective regulation of CD40-stimulation on brain-derived neurotrophic factor levels in untreated relapse-remitting MS was found to be reversible with IFN-beta1a therapy." (PMID 35456932, 2022). "Further, we examined the effect of disease on CD40 expression in B-lymphocytes and monocytes freshly isolated from the peripheral blood of MS patients with relapsing-remitting MS (RRMS) compared to age- and sex-matched healthy controls." (PMID 26068105, 2015).
renal fibrosis (4 papers, 2015 to 2020). A final common manifestation of a wide variety of chronic kidney diseases characterized by glomerulosclerosis and tubulointerstitial fibrosis. "Importantly, we noted significant improvements in renal function, including a decrease in urinary protein excretion and renal fibrosis in Cd40-deficient rats following the 2K1C procedure." (PMID 33202988, 2020). "However, the Cd40 deficiency resulted in significantly less renal fibrosis compared to Dahl S rats." (PMID 33202988, 2020). "Thus, while infiltrating T-cells may explain the persistent hypertension in the Cd40 deficient rats, our data suggest that CD40 expressed within the kidney itself plays a central role in the development of renal fibrosis." (PMID 33202988, 2020). "Transcriptional profiling by RNA-seq of isolated renal proximal tubule from the mouse model of UUO-induced renal fibrosis revealed that a section of proximal tubule acquires a proinflammatory phenotype during fibrosis, in which CD40 signaling was up-regulated." (PMID 33202988, 2020). "Interestingly, reciprocal renal transplantation confirmed that local CD40 expressed in the kidney contributed to renal fibrosis in the ischemic kidney following the 2K1C procedure." (PMID 33202988, 2020). "Ureter obstruction resulted in a large increase in renal fibrosis and macrophage infiltration markers (TGFβ1, COL1A1, and F4/80), which were unaffected by either CD40 activation or in CD40 knockout mice." (PMID 26623936, 2015).
Splenomegaly (4 papers, 2008 to 2022). Abnormal increased size of the spleen. "Surprisingly, liposomal encapsulation also appeared to decrease the toxicity of high doses of CD40 antibody as assessed by the degree of splenomegaly induced." (PMID 18523585, 2008). "Furthermore, mice deficient in TNFR1, which binds TNF and lymphotoxin α, were almost completely protected from CD40 mAb-induced loss of locomotor activity and body weight, but not from splenomegaly." (PMID 34440067, 2021). "This again is contrary to MHV-68 infections in the absence of CD40, CD40L or CD80/CD86, where splenomegaly and/or viral load during latency amplification were either similar or lower." (PMID 19621080, 2009).
squamous cell carcinoma (4 papers, 2019 to 2023). A carcinoma arising from squamous epithelial cells. "Here, we found that CD40 RNA levels were higher in squamous cell carcinomas than in other histological subtypes." (PMID 37970926, 2023). "Interestingly, higher CD40 levels, especially in squamous carcinomas, were associated to HPV positivity, which was also seen in our in silico analysis, where CD40 expression was significantly higher in HPV-positive patients." (PMID 37970926, 2023). "Interestingly, CD40, an antigen frequently lost by basal and squamous cell carcinomas during tumor escape from activated T cells, was augmented by Onco-P20 treatment." (PMID 34073987, 2021). "DDR-deficient types had lower expressions of STING1 (p = 0.01), CD28 (p = 0.020), HLA-DRB6 (p = 0.014) in adenocarcinoma, lower TNFRSF4 (p = 0.017), and TGFB1 expressions (p = 0.033) in squamous carcinoma, and higher CD40 (p = 0.012) and TNFRSF14 expressions (p = 0.022) in SCLC." (PMID 34604048, 2021).
systemic sclerosis (4 papers, 2012 to 2025). A chronic disorder, possibly autoimmune, marked by excessive production of collagen which results in hardening and thickening of body tissues. "The aim of the present study was to investigate the possible role of CD40 and CD40 ligand (CD40LG) genes in the susceptibility and phenotype expression of systemic sclerosis (SSc)." (PMID 22731751, 2012). "Nevertheless, our findings support the idea that CD40 dysregulation may be involved in immune-mediated diseases like systemic sclerosis." (PMID 40843700, 2025). "Also, B cells from patients show high expression of CD19 and CD40, whereas memory cells from systemic sclerosis patients show reduced expression of CD35." (PMID 26483788, 2015).
thyroid (4 papers, 2017 to 2024). "Transgenic mouse models constitutively overexpressing thyroidal CD40 develop more severe experimental autoimmune GD and thyrotoxicosis, whereas blockade of CD40 stimulation in experimental animal models suppresses progression to overt thyroiditis." (PMID 29254239, 2017).
toxoplasmosis (4 papers, 2010 to 2025). A parasitic disease contracted by the ingestion or fetal transmission of toxoplasma gondii. "Next, we examined whether susceptibility to toxoplasmosis in CD40−/− mice could be explained by impaired expression of IFN-γ, TNF-α and NOS2." (PMID 21217818, 2010).
transitional cell carcinoma (4 papers, 2003 to 2021). A malignant neoplasm arising from the transitional epithelium, usually affecting the urinary bladder, ureter, or renal pelvis. "The important adaptive mechanism for the occurrence and development of transitional cell carcinoma might be CD40 expression loss." (PMID 34899848, 2021). "Flow cytometry corroborated cell-surface CD40 expression, in comparison to HCT116 and urothelial cell carcinoma (UCC) line EJ10." (PMID 31815003, 2019).
triple-negative breast carcinoma (4 papers, 2020 to 2025). An invasive breast carcinoma which is negative for expression of estrogen receptor (ER), progesterone receptor (PR), and human epidermal growth factor receptor 2 (HER2). "All CD40 splice variants (V1–3) were detected in 3 out of 4 triple-negative breast cancer cell lines." (PMID 32256143, 2020). "Overall, the survival analysis that we performed, in contrast to the studies on solid tumors mentioned earlier, has shown that high CD40 expression is associated with good prognosis in triple-negative breast cancer." (PMID 32256143, 2020). "High CD40 expression was detected in the cytoplasm of hormone-receptor–positive breast cancer, whereas it was detected on the surface membrane of triple-negative breast cancer." (PMID 32256143, 2020). "To determine the effect of anti-CD40 in another tumor model that is resistant to CTLA4i and radiation used as monotherapy and shows responses in a minority of mice treated with the combination of RT+CTLA4i, we used the AT3 mouse model of triple-negative breast cancer." (PMID 37620372, 2023).
X-linked hyper-IgM syndrome (4 papers, 2010 to 2025). "Further evaluation for X-linked hyper IgM syndrome revealed normal expression of the CD40 marker, CD40 ligand, and replication function." (PMID 41044616, 2025). "X-linked Hyper-IgM syndrome occurs due to defect in CD40L that encodes for CD40 (CD154) present on activated T cells." (PMID 31572360, 2019).
acute myeloid leukemia (3 papers, 2022 to 2023). Acute myeloid leukemia (AML) is a group of neoplasms arising from precursor cells committed to the myeloid cell-line differentiation. "In contrast, FDX1 expression was negatively correlated with CD40 expression in ACC, COAD, ESCA, KICH, KIRC, KIRP, acute myeloid leukemia (LAML), PRAD, STAD, and THCA, but was positively related to this gene expression in the other six cancers." (PMID 36210836, 2022). "Particularly, DNMT and HDAC inhibitors may result to an upregulation of TAAs and of co-stimulatory molecules such as CD40, CD80, CD86 and MHC classes I and II, on tumor cells, in particular in Acute Myeloid Leukemia (AML) cell lines." (PMID 39086678, 2023).
allergic asthma (3 papers, 2021 to 2025). A asthma with a basis in a pathological type I hypersensitivity reaction. "Moreover, CD40 induces the expression of numerous signalling molecules associated with airway inflammation and remodelling in allergic asthma." (PMID 33976586, 2021). "Our findings showed that IgE-hFcεRI-dependent upregulation of co-stimulatory CD80, CD86, and CD40 on hFcεRI eosinophils would be consonant with a recent study of 32 allergic asthma subjects who had clinically beneficial responses over 16 weeks of treatment with the anti-IgE mAb, omalizumab." (PMID 39996772, 2025). "CD40 improves the sensitivity of related cells and promotes the production of proinflammatory cytokines after postexercise bronchoconstriction in patients with allergic asthma." (PMID 33976586, 2021).
angina (3 papers, 2013 to 2025). "Secondary outcome parameters: other circulating inflammatory markers (including IL-6, TNFα, VCAM-1, CD40, sCD40L, MCP-1, and MMP-9), improvement in symptoms of angina and blood stasis syndrome, and safety." (PMID 23983803, 2013).
Anxiety (3 papers, 2021 to 2026). Intense feelings of nervousness, tension, or panic often arise in response to interpersonal stresses. "Frequencies of CD40 positive (+) and CD83+ cells were significantly increased in mice under anxiety stress than in control mice (41.80 ± 7.19% vs. 25.94 ± 4.16%, p = 0.008; 27.78 ± 5.45% vs. 11.20 ± 3.88%, p = 0.008, respectively)." (PMID 33868228, 2021).